MSL3B (MSL complex subunit 3B )
Synonyms: MSL3L2; MSL3P1
Tractability: PROTAC: ubiquitination databases record sites on it.
Gene: Protein-coding gene on chromosome 2 (233,864,663 to 233,868,386, reverse strand). Ensembl gene ENSG00000293137.
Gene Ontology:
Molecular function: histone H4K16ac reader activity
Biological process: regulation of transcription by RNA polymerase II; chromatin organization; regulation of DNA-templated transcription
Cellular component: MSL complex; nucleus
Homologues: Orthologues: macaque MSL3B (92% identical), pig MSL3 (87% identical), dog MSL3 (76% identical), tropical clawed frog msl3 (72% identical), rat Msl3l2 (58% identical), mouse Msl3l2 (58% identical), Drosophila melanogaster msl-3 (21% identical), Caenorhabditis elegans mrg-1 (14% identical), Caenorhabditis elegans cec-7 (8% identical). Paralogues in human: MSL3 (88% identical), MORF4L1 (18% identical), MORF4L2 (18% identical).
Diseases named in the same sentence as MSL3B in open-access papers:
MSL3B is named in the same sentence as 6 diseases in open-access papers, as found by Europe PMC text mining. Sharing a sentence is not in itself a finding about the gene and the disease.
MSL3B shares sentences with these, for which no sentence is quoted: cancer (2 papers); renal cell carcinoma (2); gastrointestinal disease (1); migraine (1); oropharyngeal cancer (1); tumor (1).